MYCN (MYCN proto-oncogene, bHLH transcription factor)
Diseases named in the same sentence as MYCN in open-access papers (continued):
Sharing a sentence is not in itself a finding about the gene and the disease.
neuroblastoma (continued). "Here we address this by developing a model of the energy metabolism to investigate the effect of alterations in gene expression induced by overexpression of MYCN in neuroblastoma cells, based on our previously published experimental data." (PMID 40993267, 2025). "To further understand the cell state alterations in neuroblastoma resistance, we treated MYCN-amplified patient-derived xenografts (SJNB14) implanted subcutaneously into CB17/SCID mice with indisulam (25 mg/kg, 5 days on/2 days off for two weeks)." (PMID 40962798, 2025). "Given that neuroblastomas originate from neural crest derived precursors, these studies indicate the essential role of MYCN in both peripheral nervus system development and neuroblastoma development." (PMID 40365336, 2025). "Similar to MDM2, which was originally discovered from double minute chromosomes in NIH-3T3 cells, MYCN was also found to form extrachromosomal double minutes in neuroblastomas." (PMID 39802403, 2025). "Here we aim to investigate the impact of the oncogene MYCN on metabolic flux alterations in preclinical neuroblastoma models." (PMID 40993267, 2025). "The first and most widely used neuroblastoma GEMM is the TH-MYCN model, driven by MYCN overexpression under the tyrosine hydroxylase (TH) promoter." (PMID 40874091, 2025). "Although direct evidence of LIN28B’s involvement in rRNA processing in cancer is limited, it has been reported that LIN28B enhances ribosomal RNA biogenesis and ribosome function in MYCN-amplified neuroblastomas." (PMID 40265419, 2025). "The study further demonstrated the significance of the MYCN and polyamine pathway in neuroblastoma tumorigenesis by using difluoromethylornithine, an ODC inhibitor, which decreased polyamine levels." (PMID 40104501, 2025). "Conditional expression of MYCN in the neural crest increased the incidence of medulloblastoma and neuroblastoma, confirming the oncogenic role of MYCN." (PMID 39802403, 2025). "Similar decreases in cell viability were observed in KCNR and IMR-32 cells, indicating that the cohesin loading factor NIPBL is essential for the proliferation of MYCN-amplified neuroblastoma cells." (PMID 40867243, 2025). "The findings from our investigation revealed that 6-AN modulated the redox system and increased the cytotoxicity of 5-ALA-mediated PDT in MYCN-amplified neuroblastoma cells." (PMID 41291487, 2025). "We selected human MYCN as a pan-universal neuroblastoma marker, with Prph and Ube2c signifying uncommitted and malignant neuroblast populations, respectively." (PMID 40580553, 2025). "So far, only a few transcription factors have been characterized to promote EIF4EBP1 transcription in other tumor entities, including the androgen receptor in prostate cancer, ETS1 and MYBL2 in glioblastoma, and MYCN in neuroblastoma." (PMID 40670359, 2025). "Mice models with abdominal neuroblastoma tumors resulting from neural-crest-specific MYCN transgenic expression (TH-MYCN mice) have been used to study neuroblastoma." (PMID 40004600, 2025). "This level of heterogeneity is consistent with the findings in the neuroblastoma literature, where factors such as MYCN amplification, age at diagnosis, and prior treatment history are known to significantly impact survival outcomes." (PMID 39941606, 2025). "Three patients had stable disease for over four cycles, including a patient with MYCN amplified neuroblastoma with stable disease for 24 cycles." (PMID 41308010, 2025). "Recently, we have demonstrated that SP141, a small molecule that induces MDM2 degradation and inhibits MYCN protein level, exhibits several beneficial effects in neuroblastoma." (PMID 39802403, 2025). "In neuroblastoma and medulloblastoma, MYCN gene amplification directly drives MIR17HG transcription." (PMID 41473312, 2025). "In MYCN-driven neuroblastoma and medulloblastoma mouse models, the PI3K inhibitors PIK-75 and PW-12 have been shown to induce tumor apoptosis by disrupting N-Myc stability." (PMID 41244073, 2025).
neuroblastoma (continued). "In vitro, PA2G4 knockout partially reduced cell viability in neuroblastoma cell lines, with effects observed in MYCN-dependent and -independent contexts." (PMID 41002386, 2025). "Recent efforts to target MYCN in pediatric brain tumors, including neuroblastomas, medulloblastomas, high-grade gliomas, atypical teratoid/rhabdoid tumors, ependymomas, and pineoblastomas, have faced significant challenges." (PMID 40365336, 2025). "Our metabolomics data capture metabolite levels in SH-EP neuroblastoma cells with Tet-inducible MYCN expression, which were grown under three different glucose concentrations." (PMID 40993267, 2025). "Neuroblastoma can show many different chromosomal abnormalities, the most noticeable ones being related to the MYCN proto-oncogene." (PMID 40286729, 2025). "In MYCN-expressing neuroblastomas, the overexpression of LSD1 promotes an undifferentiated cellular state and correlates with poor prognosis." (PMID 40940894, 2025). "It is well‐established that ODC1‐mediated polyamine biosynthesis is one of the mechanisms by which MYCN amplification drives neuroblastoma tumor cell proliferation." (PMID 39981745, 2025). "Complementary evidence from MYCN-amplified neuroblastoma models further supports combining AURKA inhibitors and DDR inhibitors." (PMID 41561634, 2025). "A total of 87 neuroblastoma children (28 patients with MYCN+ HR, 33 patients with MYCN− HR and 26 patients with MYCN− IR or LR) and 47 HCs were enrolled to detect the miRNA levels." (PMID 41142119, 2025). "Functional studies revealed that NIPBL is essential for the proliferation of MYCN-amplified neuroblastoma cells, as its depletion significantly reduced cell viability across multiple cell lines." (PMID 40867243, 2025). "The combination of statins and phenothiazines showed strong synergistic effects in human neuroblastoma organoids, decreased tumor growth, and prolonged survival in MYCN-amplified neuroblastoma patient-derived xenografts." (PMID 41437160, 2025). "Others, like the targeting of the exosome in MYCN‐driven neuroblastoma or CTR9 in PDAC are still to be validated using compounds in vivo, but are still promising targets that promise less toxicity and better drugability than MYC proteins itself." (PMID 40488968, 2025). "The N-Myc gene MYCN amplification accounts for the most common genetic aberration in neuroblastoma and strongly predicts the aggressive progression and poor clinical prognosis." (PMID 40493396, 2025). "EccDNAs that contain segments of MYCN facilitate the amplification of MYCN in neuroblastoma through the regulation of genome remodeling." (PMID 41009369, 2025). "In contrast, in SMG samples from 6-week-old Th-MYCN+/− mice, most MYCN+ neuroblastoma cells were Ube2c+, expanding in tandem with MYCN-/Prph+ ganglion cells." (PMID 40580553, 2025). "While transcription factor–NIPBL cooperation has been proposed as a mechanism for enhancer–promoter specificity in other systems, the role of NIPBL in neuroblastoma, particularly in MYCN-driven oncogenic transcription, remains largely unexplored." (PMID 40867243, 2025). "Taken altogether, our results in MYCN-amplified neuroblastoma are consistent with others, showing a relatively cold tumor microenvironment." (PMID 39892705, 2025). "MYCN-amplified neuroblastoma shows increased production of reactive oxygen species (ROS) and relies on the glutathione redox system for ROS detoxification." (PMID 41291487, 2025). "Recently, MYCN breakpoint detection in ctDNA from patients with MYCN-amplified neuroblastomas was reported." (PMID 39760332, 2025). "Affinity proteomics and molecular docking-based studies have revealed that ceftriaxone inhibits N-Myc translation by targeting DEAD-box helicase 3 X-linked (DDX3X), thereby inducing apoptosis in MYCN-amplified retinoblastoma and neuroblastoma cells." (PMID 41244073, 2025).
neuroblastoma (continued). "This review aims to provide a theoretical foundation for future development of precise and effective therapies targeting MYCN-amplified neuroblastoma." (PMID 41244073, 2025). "In summary, these results revealed that RTA-408 exerted dramatic antitumor effects against MYCN-amplified neuroblastoma cells by promoting the degradation of N-Myc protein." (PMID 40493396, 2025). "In conclusion, using multiparametric MRI we have demonstrated that cabozantinib exhibits activity against neuroblastomas arising in both Th-MYCN and Th-MYCN/ALKF1174L mice." (PMID 40359728, 2025). "In high-risk neuroblastoma, SLC19A1 is upregulated by MYCN, enhances methotrexate uptake, and is associated with poor prognosis, indicating its potential as a therapeutic and prognostic target." (PMID 41376620, 2025). "Specifically, MYCN-amplified neuroblastoma has distinct core regulatory mechanisms, which likely result in different pathways controlling cell death and survival." (PMID 40332068, 2025). "Our study shows that induced expression of HIF2α in MYCN-amplified neuroblastoma substantially reduces MYCN protein levels and attenuates proliferation while it induces several features of noradrenergic differentiation and impedes xenograft tumor growth." (PMID 41118218, 2025). "In high-risk neuroblastoma (HRNB) cells with LIN28B knocked down, where MYCN levels were elevated, let-7 miRNA expression was still suppressed." (PMID 40104501, 2025). "Another key oncogenic member is from the MYC family: the MYCN oncogene (MYCN Proto-Oncogene, BHLH Transcription Factor), which plays a critical role in neuroblastoma, and its amplification is associated with a poor prognosis." (PMID 41155227, 2025). "Patients with the longest duration of disease control were a patient with Ewing sarcoma (5.6 months), a patient with ependymoma (10.5 months), and a patient with MYCN amplified neuroblastoma (24.8 months)." (PMID 41308010, 2025). "Neuroblastomas are characteristically highly vascularised, and the extent of tumour angiogenesis correlates with metastatic disease, MYCN amplification and a poor clinical prognosis." (PMID 40359728, 2025). "As a proof-of-concept, we leverage CRISPR-Cas9 nickase to selectively promote cancer cell death in MYCN-amplified neuroblastoma in a gene amplification-dependent manner." (PMID 40456709, 2025). "In summary, our study provides the evidence identifying KLHL37 as a crucial regulator in the progression of MYCN-amplified neuroblastoma and provides valuable insights into the pathological mechanism of how N-Myc maintains high stability in neuroblastoma." (PMID 40493396, 2025). "Neuroblastoma is classified into stages based on factors such as the degree of differentiation, patient age, and MYCN oncogene status, with MYCN amplification serving as a critical prognostic marker of risk." (PMID 40513779, 2025). "Consistent with the in vivo models and patient datasets, a significant increase in CD68 positive macrophages was identified in ATRX mutant neuroblastomas compared with MYCN-amplified or non MYCN-amplified disease." (PMID 39892705, 2025). "While it is unclear what the role of SP transcription factors is in neuroblastoma identity, one early study indicates that they are involved in driving expression of MYCN in neuroblastoma cells." (PMID 40962798, 2025). "In MYCN-amplified neuroblastoma, MYCN gene amplification drives oncogenic processes by promoting the transcription of genes necessary for tumor growth." (PMID 39802403, 2025). "The lethal response in our cultures occurred in the nanomolar concentration range, well below the recommended doses in patients and comparable to MYCN-driven neuroblastoma cell lines." (PMID 39740515, 2025). "AURKB is a direct transcriptional target of MYCN and both aurora kinases have been correlated with a poor prognosis in neuroblastoma." (PMID 40104501, 2025).
neuroblastoma (continued). "The aberrant amplification of the MYCN gene is a critical genetic alteration observed in neuroblastoma conferring poorer clinical outcomes." (PMID 40860201, 2025). "Given the central oncogenic role of MYCN, any process that can significantly reduce MYCN protein levels in an MYCN-amplified neuroblastoma would most probably also reduce tumor growth and aggressiveness." (PMID 41118218, 2025). "We previously showed that indisulam induced durable complete responses in C-MYC– and MYCN/ALKF1178L–driven neuroblastoma models under immune competent settings." (PMID 40962798, 2025). "ATRX loss-of-function from p.Gln1670* or p.Glu1984* mutations turn MYCN non-amplified neuroblastoma more aggressive and similar to what is seen in MYCN amplified neuroblastoma." (PMID 40286729, 2025). "Mechanistically, NIPBL co-occupies neuroblastoma-specific enhancers with MYCN, particularly at regulatory regions enriched for core regulatory circuitry (CRC) transcription factor binding motifs." (PMID 40867243, 2025). "To determine the importance of PA2G4 to MYCN-driven neuroblastoma in vivo, we created Th-MYCN transgenic mice harboring a deletion of the PA2G4 gene." (PMID 41002386, 2025). "In contrast, our findings in MYCN-amplified neuroblastoma show that GALNT3 is downregulated, which coincides with reduced immune cell infiltration." (PMID 39860532, 2025). "This genetic modification closely mimics the MYCN amplification observed in human neuroblastoma, leading to spontaneous tumor development." (PMID 40708972, 2025). "The discovery of MYCN overexpression in neuroblastoma cells has guided the majority of studies regarding the oncogenic functions of MYCN." (PMID 39802403, 2025). "Elevated MDM2 expression is required for high-level expression of MYCN in small-cell lung cancer, retinoblastoma, neuroblastoma, and medulloblastoma cells." (PMID 39802403, 2025). "Supporting this finding, ATP13A3 mRNA levels were significantly higher in MYCN‐amplified versus non‐MYCN‐amplified neuroblastomas." (PMID 39981745, 2025). "Zebrafish models of neuroblastoma uncovered the impact of co-expressing the MYCN oncogene and LIM domain only 1 (LMO1), which drives aggressive tumor growth and metastasis resembling high-risk human neuroblastoma." (PMID 39940643, 2025). "To experimentally validate this dependency, we used two independent small interfering RNAs (siRNAs) to deplete NIPBL in MYCN-amplified neuroblastoma cells, BE2C, KCNR, and IMR-32." (PMID 40867243, 2025). "It covers topics such as downstream gene expression, the regulation of MYCN gene expression and protein stability, and its oncogenic roles across various cancer types, with a particular emphasis on neuroblastoma." (PMID 39802403, 2025). "To further investigate the therapeutic effect of RTA-408, we introduced a patient-derived xenograft (PDX) tumor based on MYCN-amplified neuroblastoma tissue from a patient with relapsed disease." (PMID 40493396, 2025). "ADAMTS9-AS2 has also been identified as a driver of neuroblastoma differentiation through the regulation of LIN28B/let-7/MYCN signaling." (PMID 40831535, 2025). "JMJD3 inhibition has also been shown to cause the accumulation of H3K27me3, disturbing the interaction of transcription factors and resulting in the downregulation of the CDK4/6-pRB-E2F pathway and of MYCN in neuroblastoma." (PMID 40253363, 2025). "MYCN amplification, present in approximately 20% of neuroblastoma cases, is recognized as a key marker of poor prognosis and is strongly associated with aggressive disease behavior." (PMID 41228227, 2025). "The data suggest that MYCN gene amplification is often accompanied by ALK mutation activation, and the two synergistically initiate and promote the development of neuroblastoma." (PMID 40115016, 2025).
neuroblastoma (continued). "Collectively, we have established a mechanistic link between NIPBL and the MYCN-driven transcriptome, highlighting NIPBL as a potential therapeutic vulnerability to promote differentiation in high-risk neuroblastoma." (PMID 40867243, 2025). "Histopathology confirmed MYCN-amplified neuroblastoma invading the adjacent renal parenchyma, which was classified as high risk by the International Neuroblastoma Risk Group." (PMID 41235320, 2025). "The analysis revealed distinct glycosylation-related gene expression profiles that clearly differentiated MYCN-A samples from MYCN-NA samples, suggesting a potential link between the MYCN status and altered glycosylation patterns in neuroblastoma." (PMID 39860532, 2025). "For instance, ectopic expression of MYCN in neuroblastoma cells can stimulate the re-entry of quiescent cells into the cell cycle and reduce the G1 phase, also decreasing cell attachment to the extracellular matrix." (PMID 40365336, 2025). "The duration of disease control (24 months) is distinctly unusual for patients with relapsed MYCN‐amplified neuroblastoma." (PMID 41308010, 2025). "It has demonstrated remarkable efficacy, particularly in the context of MYCN-amplified neuroblastoma." (PMID 39802403, 2025). "We observed that treatment of neuroblastoma cell lines with N78 reduced N-Myc protein expression, while MYCN mRNA levels remained unchanged at the same concentration of N78." (PMID 40860201, 2025). "Human tumor specimens were obtained from 8 patients at Children’s National Hospital (CNH) diagnosed with neuroblastoma of which two were MYCN amplified." (PMID 40552293, 2025). "MYCN plays a significant role in tumorigenesis, particularly in neuroblastoma, medulloblastoma, high-grade gliomas, and atypical teratoid/rhabdoid tumor as detailed below." (PMID 40365336, 2025). "Previous studies have shown that WS6 is effective in MYCN-driven neuroblastoma models; however, its activity in other MYC-driven cancers remains to be determined." (PMID 41002386, 2025). "In the study of neuroblastoma, it was found that MYCN amplification is related to the methylation status of its binding site, and the degree of methylation is negatively correlated with the degree of gene expression." (PMID 39966875, 2025). "In summary, our study establishes NIPBL as a central regulator of MYCN-driven transcription in neuroblastoma." (PMID 40867243, 2025). "While our findings provide a valuable framework for understanding the impact of MYCN amplification on neuroblastoma progression and immune evasion, it is important to acknowledge the inherent limitations of in silico analyses." (PMID 39860532, 2025). "The FDA-approved proteasome inhibitor bortezomib (BTZ) efficiently targets neuroblastoma cell lines in a MYCN-dependent manner in vitro." (PMID 39740515, 2025). "Downstream effectors of MYCN govern proliferation, metabolism, and differentiation, making them key determinants of neuroblastoma progression." (PMID 41244073, 2025). "Aurora kinase A (AURKA) is an established oncogenic factorandtherapeutic target in neuroblastoma due to its roles in mitosis andstability of the MYCN protein." (PMID 41252673, 2025). "Knockdown of ATP13A3 alone was sufficient to prevent any DFMO‐induced compensatory increase in radiolabeled putrescine and spermidine uptake in both MYCN‐amplified and non‐MYCN amplified neuroblastoma cell lines." (PMID 39981745, 2025). "Instead, the direct MDM2-MYCN interaction significantly fuels MYCN-amplified neuroblastoma growth and progression." (PMID 39802403, 2025).